GLDC (glycine decarboxylase)
Description:
The glycine cleavage system catalyzes the degradation of glycine. The P protein (GLDC) binds the alpha-amino group of glycine through its pyridoxal phosphate cofactor; CO(2) is released and the remaining methylamine moiety is then transferred to the lipoamide cofactor of the H protein (GCSH).
Synonyms: GCSP; NKH; GCE; GCE1; HYGN1
Tractability: Small molecule: a structure with a bound ligand is known. Antibody: its Gene Ontology location is reachable by antibodies, with high confidence. PROTAC: ubiquitination databases record sites on it; its protein half-life has been measured.
Gene: Protein-coding gene on chromosome 9 (6,532,467 to 6,645,729, reverse strand). Ensembl gene ENSG00000178445.
Subcellular location: Mitochondrion
Subcellular location (Human Protein Atlas): Mitochondria; Nucleoplasm
Pathways (Reactome):
Metabolism: Glycine degradation
Gene Ontology:
Molecular function: glycine dehydrogenase (decarboxylating) activity; electron transfer activity; protein homodimerization activity; pyridoxal binding; lyase activity
Biological process: glycine catabolic process; glycine decarboxylation via glycine cleavage system; response to lipoic acid; response to methylamine; amino acid metabolic process; glycine metabolic process
Cellular component: mitochondrion; glycine cleavage complex; mitochondrial matrix
Genetic constraint (gnomAD): Loss-of-function variants: 69 observed, 77.32 expected, observed/expected ratio (o/e) 0.89, 90% interval 0.73 to 1.09. The upper end of that interval is the gene's LOEUF score, 1.09, which puts it in group 4 of 6, group 1 being the genes least tolerant of losing a copy. Missense variants: 1,059 observed, 955.98 expected, observed/expected ratio (o/e) 1.11, 90% interval 1.05 to 1.16. Synonymous variants: 422 observed, 356.81 expected, observed/expected ratio (o/e) 1.18, 90% interval 1.09 to 1.28.
Gene-disease validity (ClinGen):
ClinGen rates the evidence that GLDC causes each of these diseases.
glycine encephalopathy (autosomal recessive): Definitive. Glycine encephalopathy (GE) is an inborn error of glycine metabolism characterized by accumulation of glycine in body fluids and tissues, including the brain, resulting in neurometabolic symptoms of variable severity.
Homologues: Orthologues: chimpanzee GLDC (99% identical), macaque GLDC (99% identical), pig GLDC (94% identical), dog GLDC (94% identical), rabbit GLDC (93% identical), mouse Gldc (92% identical), rat Gldc (92% identical), guinea pig GLDC (91% identical), tropical clawed frog gldc (79% identical), zebrafish gldc (63% identical), Drosophila melanogaster CG3999 (61% identical), Caenorhabditis elegans gldc-1 (56% identical).
Diseases named in the same sentence as GLDC in open-access papers:
GLDC is named in the same sentence as 84 diseases in open-access papers, as found by Europe PMC text mining. Sharing a sentence is not in itself a finding about the gene and the disease. The quoted sentences say what the papers report.
glycine encephalopathy (21 papers, 2014 to 2024). "For instance, our group developed a zebrafish model of glycine encephalopathy carrying a mutation in a glycine metabolism enzyme (GLDC: glycine decarboxylase)." (PMID 35875659, 2022). "Congenital mutations in GCS components, such as glycine decarboxylase (gldc), cause an elevation in glycine levels and the rare disease, nonketotic hyperglycinemia (NKH)." (PMID 36551976, 2022). "Defect in glycine decarboxylase (GLDC) causes Non-ketotic Hyperglycinemia (NKH), a neurological disease associated with elevation of plasma glycine." (PMID 33524012, 2021). "The rare disease non-ketotic hyperglycinemia (NKH) additionally has a wide range of disease-causing mutations in glycine decarboxylase (GLDC), a protein that breaks down glycine." (PMID 32421718, 2020). "Loss of function mutations in GLDC are the primary cause for the rare neuro-metabolic disorder non-ketotic hyperglycinemia (NKH), accounting for approximately 85% of NKH cases." (PMID 32421718, 2020). "Missense mutations of the glycine decarboxylase gene (Gldc) are associated clinically with a metabolic disorder, Non‐ketotic hyperglycinemia (NKH) and neural tube defects (NTDs) such as exencephaly." (PMID 28056489, 2017). "The following case illustrates one of such variant reclassifications – a patient suspected to have glycine encephalopathy in whom two variants in the GLDC (OMIM 238300) gene were detected; NM_000170.2; c.2113G>A (p.Val705Met) and c.2182G>A (p.Gly728Arg)." (PMID 28116331, 2017). "GLDC had been annotated by the ClinGen Gene module as associated with glycine encephalopathy." (PMID 32228266, 2020). "Mutation of AMT or GLDC, encoding the GCS components aminomethyltransferase and glycine decarboxylase, can cause malformations of the developing CNS (neural tube defects (NTDs) and ventriculomegaly) as well as a post-natal life-limiting neurometabolic disorder, Non-Ketotic Hyperglycinemia." (PMID 33569080, 2021). "Nonketotic hyperglycinemia (NKH) is a rare, autosomal recessive metabolic disorder usually associated with mutations in genes AMT, GLDC or GCSH involved in the glycine cleavage complex." (PMID 39323869, 2024). "Here, we have developed new in silico tools to build models for the rare neurological disorder non-ketotic hyperglycinemia (NKH), which is caused by mutations in glycine decarboxylase (GLDC), a protein that degrades glycine." (PMID 33524012, 2021). "Mutations in GLDC are the most common cause of glycine encephalopathy (GCE), or nonketotic hyperglycinemia, which is frequently postnatal lethal and characterized by lethargy, hypotonia, myoclonic jerks, and apnea." (PMID 38822427, 2024). "Nonketotic hyperglycinemia (NKH) is a lethal autosomal recessive disease resulting from alterations in glycine metabolism, commonly caused by mutations in glycine decarboxylase (GLDC)." (PMID 34513771, 2021). "Glycine encephalopathy is associated with mutation in AMT, GLDC, and GCSH genes." (PMID 25029527, 2014). "Non-ketotic hyperglycinemia (NKH) is an ultra-rare (incidence 1/76,000 births) genetic, neurometabolic disorder caused by deficient enzyme activity of the glycine cleavage enzyme (GCE) (EC 1.4.4.2) due to mutations in GLDC encoding the P-protein or AMT encoding the T-protein." (PMID 38589924, 2024). "In addition, approximately 5% of patients with enzyme-proven glycine encephalopathy do not have a pathogenic variant in GLDC, AMT or GCSH genes; these cases therefore represent a variant form of NKH." (PMID 29304759, 2018). "Glycine cleavage system (GCS) catalyzes the degradation of glycine and disruption of its components encoded by GLDC, AMT and GCSH are the only known causes of glycine encephalopathy, also known as non-ketotic hyperglycinemia (NKH)." (PMID 27481395, 2016).
lung cancer (18 papers, 2012 to 2025). A malignant neoplasm involving the lung. "In clinical scenarios, abnormal activation of GLDC has been linked to unfavorable survival outcomes in lung cancer patients, and anomalous GLDC expression has been detected in various cancer types." (PMID 37242225, 2023). "Clinically, abnormal activation of GLDC is associated with poor survival in patients with lung cancer." (PMID 36275705, 2022). "At the level of the primary tumors, lung cancers expressing high GLDC expression are associated to a reduced survival." (PMID 30060526, 2018). "GLDC expression is usually upregulated in tumor patients, playing a critical role in tumorigenesis and cancer progression, such as in breast and lung cancers, hepatocellular carcinoma, and leukemia." (PMID 38585637, 2024). "In lung cancer, it has been reported that GLDC induces significant changes in glycolysis and glycine/serine metabolism, leading to changes in pyrimidine metabolism, thereby regulating the proliferation of non-small cell lung cancer cells." (PMID 36275705, 2022). "Together, these results indicate that GLDC is overexpressed in many types of cancer including lung cancer, which makes it a potential target in anticancer treatment." (PMID 29911072, 2018). "Together, these results suggest that GLDC-shAON-induced exon skipping suppresses GLDC expression, which resulted in reduced cell growth and tumorigenicity in lung cancer cells." (PMID 29911072, 2018). "Taken together, these in vivo observations agree with in vitro results and support anti-GLDC as an effective strategy in treating lung cancer." (PMID 29911072, 2018). "The mRNA and protein expression results showed that GLDC is highly expressed in these three lung cancer cell lines as compared with NL-20 lung normal cells." (PMID 29911072, 2018). "Metabolic screening of 143 non-small cell lung cancer patient samples showed a positive correlation between GLDC expression and lung cancer mortality." (PMID 27391339, 2016). "This suggests the importance of GLDC in liver tumorigenesis, and this gene has been previously reported to positively correlate with lung cancer mortality." (PMID 27391339, 2016). "Other report showed that cytosolic glycine decarboxylase was related to the tumor-initiating ability of lung cancers." (PMID 24244262, 2013). "In addition to its apparent link to diabetes, GLDC gene expression has been shown to be elevated in many cancers, including non‐small cell lung cancer, breast cancer, glioblastoma multiforme, and prostate adenocarcinoma." (PMID 34342168, 2021). "Glycine decarboxylase is critical to tumor-initiating cells in non-small cell lung cancer (NSCLC), and increased expression of this gene is associated with lower survivability among lung cancer patients." (PMID 29911072, 2018). "To determine whether GLDC is a potential target, we first compared its mRNA and protein expression in lung cancer cell lines against normal lung cells." (PMID 29911072, 2018). "Taken together, our findings suggest that the therapeutic effect of GLDC inhibition might be attributed to the reduced capacity of lung cancer cells to use pyruvate as a metabolic fuel for energy production." (PMID 29911072, 2018). "Similarly, in this project, GLDC inhibition by GLDC-shAON is able to inhibit cell growth and tumorigenesis in both lung cancer cells and tumor xenograft." (PMID 29911072, 2018). "· Altered GLDC expression has been correlated with survival time in lung cancer patients." (PMID 23375113, 2013). "Thus, our data demonstrated that Snail is a novel suppressor of the GLDC gene in lung cancer cells." (PMID 33869785, 2021). "Notably, GLDC is important for the growth of tumor‐initiating cells in lung cancer." (PMID 30614183, 2019).
lung cancer (continued). "Functional experiments have shown that GLDC is essential to lung cancer stem cells: particularly, both GLDC and LIN28B are required for cancer stem cell growth and tumorigenesis; GLDC overexpression was able to promote cell proliferation and transformation." (PMID 30060526, 2018). "Glycine decarboxylase (GLDC), PKCι, Notch3, and integrin β3-KRAS-RalB have been shown to play important roles in the acquisition and maintenance of stemness in lung cancer." (PMID 25965829, 2015). "Among entire lung cancer cells, ALDH (aldehyde dehydrogenase)-, CD133-, OCT4- and GLDC (glycine decarboxylase)-positive cells display stem cell-like activities and interfere with these targets and have been implicated to promote CSCs differentiation as well as elimination." (PMID 22489192, 2012). "The TCGA database shows that GLDC upregulation is not restricted to lung cancer." (PMID 29911072, 2018).
non-small cell lung carcinoma (17 papers, 2014 to 2025). A group of at least three distinct histological types of lung cancer, including non-small cell squamous cell carcinoma, adenocarcinoma, and large cell carcinoma. "GLDC was found to enhance glycolysis and is highly expressed in tumor-initiating-cells in non-small cell lung carcinoma." (PMID 39149564, 2024). "GLDC drives the occurrence of non-small cell lung cancer (NSCLC) and regulates the proliferation of cancer cells by promoting pyrimidine biosynthesis, glycolysis, and sarcosine production." (PMID 36770809, 2023). "Previous studies have shown that GLDC overexpression or its gene alternative splicing enhances cellular transformation and tumorigenesis and is correlated with poorer survival in non-small cell lung cancer (NSCLC)." (PMID 36275705, 2022). "GLDC also promotes non-small cell lung cancer progression by inducing glycolysis with pyrimidine metabolism." (PMID 35873461, 2022). "Tumor initiation cells in non-small cell lung cancer (NSCLC) were reported by transcriptomic analysis to possess highly elevated expression of glycine decarboxylase (GLDC), which was found to induce striking changes in glycolysis and glycine/serine metabolism." (PMID 34200553, 2021). "Endogenous accumulation of pyrimidine metabolites was reported in glycine decarboxylase-driven CD166+ cancer stem cells (CSCs) from non-small cell lung cancer (NSCLC)." (PMID 34071848, 2021). "It has been reported that GLDC is an oncogene in non-small cell lung cancer and glioma, while other studies have confirmed it is a tumor suppressor in gastric cancer and liver cancer." (PMID 34790227, 2021). "A research found that GLDC is over expressed in non-small cell lung cancer stem cells and accelerates the tumorigenesis by enhancing glycolysis and pyrimidine metabolism in non-cell lung cancer stem cells." (PMID 32699530, 2020). "For example, GLDC drives tumor-initiating cells and tumorigenesis in non-small cell lung cancer (NSCLC) by upregulation of pyrimidine biosynthesis." (PMID 30804330, 2019). "It was found that GLDC was overexpressed in non-small cell lung cancer stem cells and could enhance the tumorigenic ability of non-small cell lung cancer stem cells by enhancing glycolysis and pyrimidine metabolism." (PMID 41083822, 2025). "GLDC is involved in the pathogenesis of non-small cell lung cancer cell proliferation through pyrimidine metabolism, but this gene may be linked with changes in amino acid and nucleic acid metabolism in BRCA." (PMID 31311202, 2019). "Moreover, the metabolic enzyme GLDC is critical for tumor-initiating cells in non-small cell lung cancer (NSCLC)." (PMID 30369878, 2018). "High GLDC levels have been reported in several human cancers, including non-small-cell lung carcinoma, ovarian cancer, and germ-cell tumors; however, GLDC levels have not been studied in breast cancer." (PMID 24979213, 2014). "Glycine decarboxylase and HIF-1α expression were verified to be negative prognostic factors in primary resected early-stage non-small cell lung cancer." (PMID 35411037, 2022).
glioma (10 papers, 2021 to 2025). A benign or malignant brain and spinal cord tumor that arises from glial cells (astrocytes, oligodendrocytes, ependymal cells). "Tumor growth in nude mice intracranially injected with wild-type GLDC-reconstituted glioma cells was markedly faster than those injected with GLDC-deficient or GLDCK514Q-reconstituted cells." (PMID 34244482, 2021). "In addition, tumor growth in nude mice intracranially injected with wild-type GLDC-reconstituted U251 or U87 glioma cells was markedly faster than those injected with GLDC-deficient or GLDCK514Q-reconstituted cells." (PMID 34244482, 2021). "GLDC K514 acetylation inhibited its enzymatic activity, promoted its K33-linked polyubiquitination at K544 by NF-X1 and proteasomal degradation, and suppressed glioma tumor growth." (PMID 34244482, 2021). "Similarly, aberrantly increased GLDC expression is associated with poor prognosis and accelerates cell proliferation, invasion, metastasis and immune escape in multiple cancers, including neuroblastoma, glioma and prostate cancer." (PMID 41550650, 2025). "One previous study has revealed that GLDC acetylation participates in pyrimidines synthesis and glioma tumorigenesis." (PMID 41550650, 2025). "In glioma, mTORC1 activity was found to regulate post-translational modifications of glycine decarboxylase to modulate glycine metabolism and tumorigenesis." (PMID 36834608, 2023). "Acetylated GLDC is prone to be degraded in the proteasomes and results in impaired pyrimidine synthesis and growth inhibition of gliomas." (PMID 36295820, 2022). "Our finding reveals critical roles of post-translational modifications of GLDC in regulation of its enzymatic activity, glycine metabolism and tumorigenesis, and provides potential targets for therapeutics of cancers such as glioma." (PMID 34244482, 2021). "However, ACAT1 inhibits glioma tumorigenesis through catalyzing glycine decarboxylase K514 acetylation, which suggests the role of ACAT1 in tumor progression is still a matter of debate and warrants further investigation." (PMID 40166933, 2025). "Finally, we find that GLDC K514 acetylation inhibits glycine catabolism, pyrimidines synthesis and glioma tumorigenesis." (PMID 34244482, 2021). "GLDC deficiency dramatically inhibited glioma cell proliferation, which was reversed by reconstitution with wild-type GLDC but not GLDCK514Q." (PMID 34244482, 2021). "Moreover, SIRT3 induces deacetylation of glycine decarboxylase (GLDC) and promotes glycine catabolism and pyrimidine synthesis, which is crucial for the proliferation of human glioma cells." (PMID 38773972, 2024).
breast carcinoma (9 papers, 2014 to 2025). "We used western blotting and immunohistochemistry to examine five serine-/glycine-metabolism–associated proteins (PHGDH, PSAT, PSPH, SHMT, and GLDC) in six breast cancer cell lines and 709 breast cancer cases using tissue microarray (TMA)." (PMID 24979213, 2014). "Based on the TCGA-TNBC dataset analysis, four out of the five model genes (SDS, RDH12, IDO1, and GLDC) demonstrated significantly elevated expression levels in breast cancer samples." (PMID 40217479, 2025). "The consistent result that the expression of GLDC was increased in breast cancer, especially in TNBC tissues, was obtained by utilizing the UALCAN database." (PMID 36275705, 2022). "It has been shown that GLDC is a metabolic oncogene and its expression is strongly correlated with rates of cancer proliferation and greater mortality, e.g., in breast cancer." (PMID 30641895, 2019). "According to previous reports, these enzymes are highly expressed in several human tumors: PHGDH in breast cancer and melanoma and GLDC in lung cancer." (PMID 24979213, 2014). "GLDC was also expressed at differing levels in different molecular subtypes of breast cancer." (PMID 24979213, 2014). "In summary, we retrospectively identified five bone metastases‐related genes (KRT23, REEP1, SPIB, ALDH3B2, and GLDC) and constructed a gene expression signature‐based nomogram (GESBN) model for breast cancer patients by bioinformatics analysis." (PMID 30575323, 2019). "Appreciably, breast cancer stromal components expressed elevated PSPH, SHMT1, and GLDC levels." (PMID 24979213, 2014).
hepatocellular carcinoma (9 papers, 2019 to 2025). A malignant tumor that arises from hepatocytes. "Knockdown of glycine decarboxylase represses the growth of the tumor by regulating mitochondrial protein lipoylation in hepatocellular carcinoma (HCC)." (PMID 36275705, 2022). "In hepatocellular carcinoma cells, GLDC regulated the autophagy and invasion of cells via silting miR-30d-5p." (PMID 35155437, 2022). "To examine this possibility, we measured GLDC gene expression in H4IIe rat hepatoma cells after treatment with insulin." (PMID 34342168, 2021). "We previously reported that GLDC downregulation enhances hepatocellular carcinoma (HCC) progression and intrahepatic metastasis through decreasing ROS-mediated ubiquitination of cofilin." (PMID 30804330, 2019). "The function of GLDC in the tumorigenesis of hepatocellular carcinoma (HCC) is conflicting." (PMID 39781465, 2025). "In hepatocellular carcinoma (HCC), the target of miR-30d-5p, glycine decarboxylase (GLDC), was closely related to the prognosis of HCC patients, and was considered as a separate factor for analysis in all probability." (PMID 35155437, 2022).